STAT3 (signal transducer and activator of transcription 3)
Diseases named in the same sentence as STAT3 in open-access papers (continued):
Sharing a sentence is not in itself a finding about the gene and the disease.
rhabdomyosarcoma (20 papers, 2007 to 2025). A rare aggressive malignant mesenchymal neoplasm arising from skeletal muscle. "We detected the protein expression of STAT3 in CD8+ T cells isolated from both rhabdomyosarcoma-bearing wild-type and APN−/− mice." (PMID 35530361, 2022). "Taken together, we substantiated that APN deficiency directly maintains the activation of CD8+ T cells to inhibit rhabdomyosarcoma growth by suppressing STAT3 activation, indicating a promising APN-based therapy for the treatment of rhabdomyosarcoma." (PMID 35530361, 2022). "The phosphorylation of STAT3 in CD8+ T cells from APN−/− mice with rhabdomyosarcoma was significantly suppressed compared to that in rhabdomyosarcoma-bearing wild-type mice, suggesting that APN deficiency inhibited STAT3 activation in CD8+ T cells." (PMID 35530361, 2022). "In the present study, we observed a lower expression of p-STAT3 in CD8+ T cells isolated from rhabdomyosarcoma-bearing APN−/− mice, which was also accompanied by higher IFN-γ and lower IL-10 in the serum." (PMID 35530361, 2022). "Bazedoxifene also inhibited rhabdomyosarcoma tumor growth in vivo via blocking of gp130 signaling and subsequent attenuation of STAT3 phosphorylation and transcription of STAT3 downstream genes." (PMID 34149710, 2021). "Accordingly, treatment with STAT3 inhibitor, XZH-5, caused suppression of BCL-2, BCL-XL, and Survivin, and resulted in increased apoptosis in rhabdomyosarcoma cells." (PMID 31652776, 2019). "As the major effector of GP130, STAT3 activation has been detected in many primary rhabdomyosarcoma and rhabdomyosarcoma cell lines." (PMID 28672024, 2017). "The results demonstrated that Bazedoxifene decreased the level of constitutively phosphorylated STAT3 (Y705) in all three rhabdomyosarcoma cell lines." (PMID 28672024, 2017). "We and others have demonstrated that persistent phosphorylated STAT3 is frequently detected in many types of human cancer including rhabdomyosarcoma and is critical for survival and tumor growth of rhabdomyosarcoma." (PMID 28672024, 2017). "Bazedoxifene effectively blocks constitutive STAT3 activation, induces apoptosis, and inhibits human rhabdomyosarcoma cells growth in vitro or in vivo, offering an attractive therapeutic approach to rhabdomyosarcoma." (PMID 28672024, 2017). "Bazedoxifene also exhibited inhibitory effect on STAT3 activation induced by IL-6 in RH5 rhabdomyosarcoma cells with expressing lower STAT3 phosphorylation and cultured in serum-free medium." (PMID 28672024, 2017). "The fact that Bazedoxifene significantly decreased STAT3 phosphorylation in vitro or in vivo and repressed STAT3 DNA binding activity in rhabdomyosarcoma cells suggested its potency." (PMID 28672024, 2017). "Ponatinib inhibits FGFR phosphorylation and subsequent STAT3 phosphorylation, inducing increased apoptosis in rhabdomyosarcoma cells and inhibition of tumor growth in mice." (PMID 24743778, 2014). "The STAT3 signaling pathway is constitutively activated in each of three rhabdomyosarcoma cell lines tested, and two small-molecule compounds inhibited both STAT3 activity and cell proliferation and viability." (PMID 21559261, 2011). "The compound also exhibited higher potency at inhibiting proliferation and STAT3 DNA binding activity than curcumin and other JAK/STAT3 inhibitors in human rhabdomyosarcoma cells." (PMID 21443800, 2011). "Our study clearly indicated that APN deficiency could enhance the immune response of CD8+ T lymphocytes to inhibit rhabdomyosarcoma growth by suppressing STAT3 activation." (PMID 35530361, 2022). "Subsequently, we administered the STAT3 inhibitor Stattic to rhabdomyosarcoma-bearing wild-type mice, and observed a remarkable tumor growth inhibition, and the frequency of CD8+ as well as CD8+IFN-γ+ T cells in the spleen and lymph nodes were markedly upregulated." (PMID 35530361, 2022).
rhabdomyosarcoma (continued). "We observed both miR-21 and miR-181b gene expression were dramatically reduced in RH30 and RH28 rhabdomyosarcoma cell lines by Bazedoxifene treatment, which was consistent with the report that miR-21 expression was strongly suppressed by silence of STAT3 siRNA." (PMID 28672024, 2017). "We also observed overexpression of constitutively active STAT3 protein rescued the cell viability of human rhabdomyosarcoma cells reduced by Bazedoxifene, providing more supportive evidence for the suggestion that Bazedoxifene acts through IL-6/GP130 signaling pathway." (PMID 28672024, 2017). "In the present study, we have for the first time demonstrated Bazedoxifene suppressed persistent STAT3 phosphorylation, decreased downstream gene expression, and induced apoptosis in human rhabdomyosarcoma cell lines expressing persistent STAT3 phosphorylation." (PMID 28672024, 2017). "Furthermore, oral administration of Bazedoxifene significantly suppressed tumor growth and expression of STAT3 phosphorylation in nude mice bearing established human rhabdomyosarcoma xenograft." (PMID 28672024, 2017). "Interestingly, loss of messenger RNA and protein expression of survivin, an inhibitor of apoptosis, as well as decreased STAT3 DNA binding activity was observed in human rhabdomyosarcoma cells treated with FLLL32." (PMID 21443800, 2011). "Interestingly, celecoxib, a cyclooxygenase-2 inhibitor, also binds to the SH2 domain of STAT3 and competitively inhibit native peptide binding, leading to suppressed tyrosine phosphorylation and reduced cell viability and migration in human rhabdomyosarcoma cells." (PMID 24743778, 2014). "In human rhabdomyosarcoma (RD) cells, shRNA-mediated STAT3 interference enhances EV71 replication, whereas STAT3 overexpression inhibits viral replication, demonstrating that STAT3 suppresses EV71 replication in RD cells." (PMID 41488475, 2025). "We also found that inhibition of STAT3 activation in vivo by STAT3 inhibitor greatly increased CD8+ and CD8+IFN-γ+ T cells in the spleen and lymph nodes of rhabdomyosarcoma-bearing wild-type mice." (PMID 35530361, 2022). "Downstream targeted genes of STAT3 such as CYCLIN D1, SURVIVIN, and BCL-XL in RH30, RD, and RH28 rhabdomyosarcoma cell lines were down-regulated when treated with Bazedoxifene." (PMID 28672024, 2017). "All these results further validated the inhibitory effects of Bazedoxifene on GP130 mediated STAT3 activation, suggesting the ability of Bazedoxifene to block IL-6/GP130/STAT3 signaling in rhabdomyosarcoma cells." (PMID 28672024, 2017). "In order to study the effect of GP130 inhibition, we first examined STAT3 phosphorylation in RD and RH30 human rhabdomyosarcoma cell lines treated with an anti-GP130 antibody." (PMID 28672024, 2017). "Bazedoxifene was evaluated for its inhibitory effect on IL-6/GP130/STAT3 signaling in RH30, RD, and RH28 rhabdomyosarcoma cell lines expressing elevated P-STAT3 levels." (PMID 28672024, 2017). "In rhabdomyosarcoma, the fusion protein PAX3-FKHR directly interacts with Stat3 and changes gene expression profiles that are normally regulated by JAK/STAT signaling pathways." (PMID 17598902, 2007). "In summary, this study demonstrated that APN deficiency could promote CD8+ T cell activation and their cytotoxicity to kill tumors via inhibiting the STAT3 signaling pathway, and proved that targeting APN had potential in the treatment of rhabdomyosarcoma." (PMID 35530361, 2022). "LY5 was evaluated in vitro demonstrating good biologic activity against rhabdomyosarcoma, osteosarcoma and Ewing’s sarcoma cell lines at high nanomolar/low micromolar concentrations, as well as specific inhibition of STAT3 phosphorylation without effects on other STAT3 family members." (PMID 28750090, 2017).
tuberculosis (20 papers, 2015 to 2025). A chronic, recurrent infection caused by the bacterium Mycobacterium tuberculosis. "In study groups of tuberculosis patients from the same region in Ghana, we detected constitutive STAT3 phosphorylation in T cells from tuberculosis patients associated with high IL-6 plasma concentrations." (PMID 36650358, 2023). "Own previous studies provided evidence that aberrant high serum cytokines (i.e., IL-6, IL-10) in tuberculosis can affect T-cell functions, e.g., by causing constitutive STAT3 phosphorylation, in tuberculosis patients." (PMID 35759173, 2023). "Additionally, the formation of foamy macrophages has been linked to STAT3, suggesting that STAT3 inhibitors could potentially play a role in macrophage polarization in tuberculosis." (PMID 32858811, 2020). "Conversely, both CD40 agonists and STAT3 inhibitors have shown potential for translation into tuberculosis research." (PMID 32858811, 2020). "It has also been reported that p38-MAPK, NFκB and STAT3 play key roles in tissue destruction in patients with tuberculosis." (PMID 27926504, 2017). "Similarly, studies have shown that STAT3 activation does correlate to impaired T cell function in tuberculosis patients." (PMID 32858811, 2020). "In this, study we sought to explore the expression of SOCS3 and STAT3 in TB patients in comparison to their healthy contacts when exposed to the wild type mycobacterium tuberculosis." (PMID 35839170, 2022). "Our and others previous studies implied that STAT3 had a great effect on fast-acting innate immunity against tuberculosis (TB)." (PMID 34307193, 2021). "In TB immunity, the pleiotropic function of STAT3 plays a major role in the activation of anti-inflammatory program in myeloid cells as well as in the differentiation and activation of T cells, resulting in the control of M. tuberculosis infection." (PMID 27384401, 2016). "In an anti-tuberculosis drug-induced liver injury rat model, pyrrolidine dithiocarbamate effectively decreased the serum level of cytokines (TNF-α, IL-1β, and IL-6) by repressing the phosphorylation of JAK2 and STAT3." (PMID 38543164, 2024).
acute lung injury (19 papers, 2014 to 2026). A condition of lung damage that is characterized by bilateral pulmonary infiltrates (pulmonary edema) rich in neutrophils, and in the absence of clinical heart failure. "JAK2 and STAT3 were verified as a hub pathway to modulating oxidative stress, inflammation, and cell apoptosis in a model of bleomycin-induced acute lung injury rat." (PMID 35132912, 2022). "Inhibition of STAT3 activity improved the pulmonary inflammatory response in LPS-induced acute lung injury (ALI)." (PMID 36120307, 2022). "It has been reported that STAT3 blocker inhibits the LPS-mediated inflammatory response in mice with acute lung injuries (ALI)." (PMID 31213027, 2019). "SOCS3 (suppressor of cytokine signaling 3) is a negative regulator of JAK/STAT3 signaling pathway and participates in the regulation of lung inflammation in a mouse model with acute lung injury (ALI)." (PMID 29284516, 2017). "In addition, phosphorylated STAT3 could upregulate the expression of SLC7A11 and reduce ferroptosis, thereby improving the pathological processes associated with acute lung injury." (PMID 34692796, 2021). "In the rat model of acute lung injury (ALI), anisodamine suppressed bleomycin-induced inflammation, oxidative stress, and apoptosis in ALI rats by inhibiting the JAK2/STAT3 pathway." (PMID 39857375, 2025). "Acute lung injury (ALI) is a lethal disease with diffuse lung inflammation, in which JAK/STAT3 signaling has been well recognized for its role in initiating and amplifying inflammatory processes." (PMID 32091104, 2020). "In addition to the MAPK pathway, signal transducer and activator of transcription-3 (STAT3), a member of the cytoplasmic family of STATs, is also key to the development of ILDs, such as acute lung injury (ALI)." (PMID 25371731, 2014).
glomerulosclerosis (19 papers, 2011 to 2025). A hardening of the kidney glomerulus caused by scarring of the blood vessels. "Stimulation of HRMC with IL‐6 enhanced their proliferation and the expression of glomerulosclerosis‐associated fibronectin and collagen IV via signal transducer and activator of transcription 3 (STAT3) activation." (PMID 33043579, 2020). "Luteolin can improve glomerulosclerosis and renal interstitial fibrosis in the db/db mice mainly by inhibiting the STAT3 pathway." (PMID 37954274, 2023). "Inflammatory cytokines such as IFN γ, IL-6, and TNF overactivated STAT1, STAT3, and NF-κB transcription factors to promote glomerulosclerosis and renal interstitial fibrosis." (PMID 34194519, 2021). "IRE1/JNK stable knock‐down in HK‐2 cells and shRNA‐mediated STAT3 depletion in HRMC confirmed their role in inflammation/glomerulosclerosis." (PMID 33043579, 2020). "Netrin-1 also suppressed AKI-induced tubular atrophy, interstitial fibrosis, vascular dropout, and glomerular sclerosis through suppression of STAT3 and JNK signaling and IL-6 expression in tubular epithelial cells." (PMID 27176224, 2016). "In summary, the regions showing activation of STAT1, STAT3 and NFκB during aging suggests a possible role for these transcription factors in the progression of glomerulosclerosis and renal interstitial fibrosis during aging." (PMID 26678048, 2015). "Since ECM expansion and mesangial proliferation are shown to be key components of glomerulosclerosis, STAT-3 inhibition was investigated for inhibition of glomerulosclerosis in many different kidney diseases such as diabetic or obstructive nephropathy in an animal model." (PMID 36374911, 2022). "In addition, suppression of IL-6/STAT3 signaling suppressed acute kidney injury-induced interstitial fibrosis and glomerulosclerosis." (PMID 35491874, 2022). "Previously, it also indicated that curcumin could reduce glomerular sclerosis and albuminuria in diabetic mice models by blocking the phosphorylation of STAT3." (PMID 35956419, 2022). "Thus, this study showed that glomerulosclerosis and interstitial fibrosis are regulated by STAT3 decoy ODNs in a UUO mouse model." (PMID 33806080, 2021). "In addition, we previously reported that STAT3 is involved in the development of glomerulosclerosis in experimental proliferative glomerulonephritis." (PMID 21445358, 2011). "Luteolin may ameliorate glomerulosclerosis and interstitial fibrosis in db/db mouse models by inhibiting the inflammatory response and oxidative stress through suppressing signal transducer and STAT3 activation." (PMID 40391375, 2025). "Luteolin might ameliorate glomerulosclerosis and interstitial fibrosis in db/db mice models by inhibiting the inflammatory response and oxidative stress through repressing signal transducer and activator of transcription 3 (STAT3) activation." (PMID 35408760, 2022). "The activation of STAT3 in renal glomerular and mesangial cells the increased the production of TGF-β1, collagen IV, and fibronectin, resulting in glomerulosclerosis in DN." (PMID 33691614, 2021).
invasive breast carcinoma (19 papers, 2005 to 2025). A carcinoma that infiltrates the breast parenchyma. "The elevated levels of STAT3 phosphorylation have been shown to be associated with regulation of apoptosis, cell-cycle progression, and tumor angiogenesis in invasive breast cancer tissues." (PMID 24886617, 2014). "In GSEA using Breast Invasive Carcinoma data (TCGA, Firehose Legacy), the ‘STAT3_02 gene set’ representing STAT3 target genes was enriched in patients with high HMGB1 expression compared to those with low HMGB1 expression." (PMID 40389855, 2025). "The GEPIA2 database showed that the expression levels of STAT3 were different among the different breast invasive carcinoma (BRCA, P = 0.0359) and ovarian serous cystadenocarcinoma (OV, P = 0.0213) stages." (PMID 36977736, 2023). "STAT3 phosphorylation at sites T715 and T716 was higher, but it was lower at Y704 than those in normal tissues in breast invasive carcinoma (BRCA)." (PMID 36977736, 2023). "Studies on invasive breast carcinoma demonstrated a correlation between STAT3 activation and Survivin expression." (PMID 29348886, 2017). "The transcription levels of STAT3 in ductal BC and invasive breast carcinoma stroma were lower than that in breast tissues (Fold changes were −2.176 and −11.013, respectively)." (PMID 28422733, 2017). "Expression of STAT1 and STAT3 were measured by quantitative immunofluorescence in invasive breast cancers and matched lymph nodes." (PMID 24728078, 2014). "In addition, IL-6 activates MDSCs through the STAT3-NF-κB-IDO pathway in invasive breast cancer." (PMID 36249057, 2022).
systemic sclerosis (19 papers, 2015 to 2026). A chronic disorder, possibly autoimmune, marked by excessive production of collagen which results in hardening and thickening of body tissues. "Considering its wide-ranging regulatory influence, it is understandable that the dysregulation of STAT3 signaling has been implicated in the development of numerous diseases, including systemic sclerosis." (PMID 38790215, 2024). "Mice with overexpressed p-STAT3 have been described as a model of systemic sclerosis associated with organ fibrosis." (PMID 36324154, 2022). "A single study conducted in Spain has shed light on the potential involvement of the STAT3 gene polymorphism, specifically the SNP STAT3 (rs4796791) locus, in the development of systemic sclerosis (SSc)." (PMID 38790215, 2024). "Signal transducer and activator of transcription 3 (STAT3) is phosphorylated by various kinases, several of which have been implicated in aberrant fibroblast activation in fibrotic diseases including systemic sclerosis (SSc)." (PMID 29066712, 2017). "IFN-γ, as a pro-inflammatory cytokines, induces the expression of specific EMT-related genes through STAT3 pathway in Systemic sclerosis, which is a complex disease characterized by vascular alterations, activation of the immune system and tissue fibrosis." (PMID 25704671, 2015). "In addition, our results are in line with the results of Morin and co-workers, showing that NCL reduced the STAT3 pathway in a mouse model of systemic sclerosis." (PMID 37242480, 2023). "STAT3 is a transcription factor that is activated in fibrotic diseases such as systemic sclerosis." (PMID 29066712, 2017). "In a recent work on patients with RA (n = 29) and Systemic Sclerosis (n = 21), the former showed a higher baseline level of STAT1 and STAT3 phosphorylation in CD3+ T cells and monocytes compared with healthy controls." (PMID 35958600, 2022). "The same signaling is observed in systemic sclerosis (SS), where TGF-β1 induces JAK2 phosphorylation, which then interacts with phosphorylated STAT3 to induce fibrotic responses." (PMID 34207510, 2021). "Other studies in human fibroblasts and mouse models of systemic sclerosis describe JAK2 activation by TGF-β1, which in turn phosphorylates STAT3 and leads to its nuclear translocation." (PMID 34207510, 2021). "Interestingly, in fibrotic skin of patients with systemic sclerosis, TGF-β downregulates the expression of SOCS3, which results in activation of STAT3." (PMID 34941574, 2022). "For instance, in systemic sclerosis (SSc), IL6 inhibition reduces dermal thickening and downregulates fibrotic markers (e.g., α-smooth muscle actin) by suppressing the TGF-β/STAT3 axis." (PMID 41544047, 2026). "Further, STAT3 regulates IL-6–mediated and TGF-β1–mediated myofibroblast differentiation in murine lung fibroblasts, and inhibition of STAT3 was found to reduce TGFβ1-induced FMT in fibroblasts, and ameliorate skin fibrosis in two mouse models of systemic sclerosis." (PMID 34207510, 2021).